SOX2 (SRY-box transcription factor 2)
Diseases named in the same sentence as SOX2 in open-access papers (continued):
Sharing a sentence is not in itself a finding about the gene and the disease.
metastatic tumors (12 papers, 2011 to 2021). "In our two armed, matched collection of CCs we demonstrated that high levels of both SOX2 and nuclear β-catenin expression, respectively, were associated significantly with metastatic disease." (PMID 22168803, 2011). "The apparent role of SOX2 as an inhibitor of EMT during embryonic development is opposite of its role as a promoter EMT in metastatic neoplasms, even though many of the same miRNAs are involved." (PMID 25156079, 2014). "Significantly higher expression of SOX2 was observed in primary CRC tissues and metastatic tumor tissues compared to paratumoral tissues with 80% of the analyzed primary tumor samples." (PMID 32927768, 2020). "The fact that the anti-Sox-2, anti-N-cadherin and anti-ALDH1 antibodies are human specific confirmed the human nature of the metastatic tumors." (PMID 29416775, 2018). "Significantly higher expression of Sox2 was observed in the primary CRC tissues and metastatic tumor tissues as compared to paratumoral tissues with 80.85% of the analyzed primary tumor tissues exhibiting elevated Sox2 expression." (PMID 29228716, 2017). "Our study is consistent with a wide variation of Sox2 expression;, some metastatic tumors had widespread Sox2 nuclear immunoreactivity; others, however, had none." (PMID 25713758, 2015).
microcephaly (12 papers, 2016 to 2024). A congenital or acquired developmental disorder in which the circumference of the head is smaller than normal for the person's age and sex. "Tcf4 binds together with microcephaly-associated transcription factors Smad4, Sox2, Chd7 and Ep300 to active enhancers at primary microcephaly genes Mcph1 and Wdr62." (PMID 28375211, 2017). "Our study suggests that ZIKV may cause microcephaly by depleting the founding population of Sox2+ NPC, which are highly susceptible to the virus." (PMID 28008958, 2016). "We also noted that 34 of the genes differentially regulated by both wt Sox2 and constitutively SUMOylated Sox2_K247R-SUMO2 are involved in human syndromes linked to microcephaly." (PMID 38507426, 2024). "In this study, I will focus on two members of the SOXB1 group (SOX2 and SOX3) and two members of the SOXC group (SOX4 and SOX11) for their associations with microcephaly." (PMID 38094004, 2023). "In any case, a relevance of Trappc9 expression in NSCs is implied by the finding of reduced numbers of Sox2-positive stem cells in the subventricular zone and hippocampal subgranular zone of knock-out mice, which might be linked to their microcephaly phenotype." (PMID 36313557, 2022). "It has been reported that SOX2 transcriptionally regulates PQBP1, an intellectual disability–microcephaly causative gene, in neural stem progenitor cells (NSPCs)." (PMID 32560273, 2020). "A SOX2-bound neural enhancer within the Akt3 gene is connected to the Zbtb18 (ZFP238 in man) TF gene, whose mutation causes microcephaly in man and mouse; in man, deletions including AKT3, or translocations separating AKT3 from ZFP238 also cause microcephaly." (PMID 30849367, 2019).
adenoma (11 papers, 2016 to 2025). A neoplasm arising from the epithelium. "Our data demonstrate that KP-driven hyperplastic lesions and adenomas transformed from club cells are positive for SOX2, but SOX2 expression becomes significantly decreased and partially lost in more advanced lesions." (PMID 38093367, 2023). "Immunohistochemistry for SOX2 has shown that it is expressed in a minority of adenoma cases and all of them were with high-grade dysplasia." (PMID 31623346, 2019). "For SOX2, staining was decreased in adenomas after fulvestrant, anastrozole, and the combination, but this effect was not as strong in preneoplasias." (PMID 28445992, 2017). "FOXM1 accelerated tumor growth, induced progression from benign adenomas to invasive, metastatic adenocarcinomas, and induced SOX2, a marker of poorly differentiated tumor cells." (PMID 29267283, 2017). "Both, Pax7 (P < 0.005) and Sox2 (P < 0.001) were significantly enriched in CD15high adenomas when compared to CD15low tumors." (PMID 27894339, 2016). "Work by Mertens and coworkers reported the identification of a side population within human adenomas that, when purified of endothelial and immune cells, expressed stemness markers such as SOX2, NESTIN and CXCR4 and epithelial–mesenchymal transition-linked factors." (PMID 28855316, 2018). "However, the clinical utility of these findings is limited since oncogenic β-catenin mutations used to propagate adenomas from Sox2+ cells have not been identified in human PAs." (PMID 27894339, 2016). "The presence of SOX2, Nestin, and CD133 was evaluated across WDLD tumors, immature PIT-1 lineage tumors, and classically differentiated adenomas using immunohistochemistry and RT-qPCR." (PMID 40643539, 2025). "In previous studies on KP GEMMs, it was found that bronchiolar hyperplasia and adenoma derived from CC10+ club cells showed positive staining for SOX2, but SOX2 expression was downregulated in adenocarcinoma, leading to LUAD lineage identity." (PMID 38093367, 2023). "All investigated and expressed target genes, CDKN1B, PTPN13, RND3, SOX2 and ZEB2, were down-regulated in adenoma compared to normal mucosa of CRC N0, except ONECUT2 and TGFB2, which were up-regulated." (PMID 31623346, 2019). "In adenomas, differential expression in comparison with CRC N0 was also observed for ZEB2 (p = 0.034) and SOX2 (p = 0.046), and in comparison with CRC N+, ONECUT2 (p = 0.006) and RND3 (p < 0.001)." (PMID 31623346, 2019). "In contrast to adenoma, investigated target genes CDKN1B, PTPN13, RND3, SOX2 and ZEB2 were up-regulated in CRC N0, except ONECUT2 and TGFB2, which were down-regulated." (PMID 31623346, 2019). "The majority of target genes (CDKN1B, PTPN13, RND3, SOX2 and ZEB2) were down-regulated in adenoma compared to normal mucosa." (PMID 31623346, 2019). "Although SOX2 and POU5F1 expression in adenoma tissue and cell cultures was very low, it was detectable in all samples." (PMID 27340409, 2016). "Moreover, PTPN13, SOX2 and ZEB2 showed detectable expression only in two out of 10 adenoma cases, whereas ONECUT2 and TGFB2 were up-regulated." (PMID 31623346, 2019). "Similarly, both of our cases that showed expression of SOX2 (also showing expression of PTPN13 and ZEB2) were adenomas with high-grade dysplasia." (PMID 31623346, 2019). "In lung preneoplasias and adenomas of tobacco carcinogen exposed mice, the anti-estrogen fulvestrant and/or the aromatase inhibitor anastrozole blocked FGF2 and FGF9 secretion, and reduced expression of the stem cell markers SOX2 and nanog." (PMID 28445992, 2017). "Moreover, PTPN13, SOX2 and ZEB2 were expressed only in two out of 10 samples of adenoma, so a calculation of statistical significance would not be appropriate." (PMID 31623346, 2019).
adenoma (continued). "In contrast to previous studies, these human adenoma cells failed to expand when xenografted into SCID mice; however, they could identify a similar side population in the AtT20 pituitary tumour cell line, which expressed SOX2 and CXCR4, and can form de novo tumours in xenograft transplantations." (PMID 28855316, 2018).
teratocarcinoma (11 papers, 2015 to 2025). A germ cell tumor characterized by the presence of an embryonal carcinoma component and a teratoma component. "In NCCIT cells, which are Sox2-expressing teratocarcinoma cells, HERV-K Gag mRNA was constitutively expressed." (PMID 40980324, 2025). "WX8 reduced the rate of teratocarcinoma formation from injected human ECCs and inhibited the proliferation of undifferentiated Ki67-, OCT4-, and SOX2-positive PSCs within the resulting teratocarcinomas." (PMID 40541178, 2025). "Immunolabelling of cytokeratins and Sox2 identified ectodermal as well as endodermal cell populations as malignant cell populations in this teratocarcinoma." (PMID 40217475, 2025). "Previously, we reported that HERV-K LTR5Hs were activated in Sox2-expressing teratocarcinoma cells (NCCIT cells)." (PMID 40980324, 2025). "Ntera, a human teratocarcinoma cell line, served as the positive control for both Sox2 and Oct4 detection." (PMID 25868977, 2015). "So far only cells that express pluripotency gene regulatory network factors, including Oct4, Sox2 and Nanog, have been shown to produce teratocarcinomas." (PMID 26453549, 2015). "In addition, we found that treatment with MS-275 significantly reduced the percentage of cells expressing OCT4, SOX2 and Nanog in NB and in a high stemness phenotype teratocarcinoma cell line." (PMID 28235409, 2017). "In contrast, another study in a different teratocarcinoma, Tera-1, found that a HERV LTR co-opted to regulate the PRODH gene exhibited an enhancer effect in responsive to Sox2 and not NF-κB, suggesting that NF-κB activation alone might not greatly alter HERV expression." (PMID 31333597, 2019).
leukemia (10 papers, 2015 to 2023). A malignant (clonal) hematologic disorder, involving hematopoietic stem cells and characterized by the presence of primitive or atypical myeloid or lymphoid cells in the bone marrow and the blood. "Correspondingly, the transcript-level expressions of stem cell-associated genes, including OCT4, KLF4, BMI1, NANOG and SOX2, were significantly increased in leukemia cells upon treatment with exosomes from BM-MSCs." (PMID 33789743, 2021). "Our results showed that ampelopsin suppresses the expression of leukemia stemness markers, including Oct4, Sox2, CD44, and CD133, in HL60 and K562 cells." (PMID 33924032, 2021). "Dissection of the functional effects of OSKM shows that Klf4 and Sox2 play dominant roles compared to c-Myc and Oct4 in elimination of leukemia cells." (PMID 31811153, 2019). "Sox2 and Klf4, instead of c-Myc, appear to play a major role in the elimination of leukemia cells, at least for the leukemia type tested in our study." (PMID 31811153, 2019). "Among the genes containing such sequences, SOX2 is the most likely to be expressed in the hematopoietic progenitor cells present in leukemia cell lines." (PMID 27551915, 2016). "We verified the expression of SOX2 in the 4 leukemia cell lines investigated in this study and in PBMC from 2 healthy donors." (PMID 27551915, 2016). "Moreover, ampelopsin suppressed the expression levels of leukemia stemness markers, such as Oct4, Sox2, CD44, and CD133." (PMID 33924032, 2021). "Here, we test whether leukemia cells can be reprogrammed in vivo using the canonical reprogramming transcription factors-Oct4, Sox2, Klf4, and c-Myc (termed as OSKM)." (PMID 31811153, 2019). "Furthermore, colony assay demonstrated that overexpression of Sox2 or Klf4 alone significantly reduced the clonal growth of leukemia cells in vitro." (PMID 31811153, 2019). "Similarly the expression of SOX2 protein was confirmed by western blotting in the four leukemia cell lines and PBMC." (PMID 27551915, 2016). "The SOX2 gene was indeed expressed in all cells leukemia and normal PBMC." (PMID 27551915, 2016). "Furthermore, ampelopsin suppressed the expression of leukemia stemness markers, including Oct4, Sox2, CD44, and CD133, in both cell lines, suggesting that ampelopsin exerts its chemotherapeutic effects by regulating both apoptosis and stemness of leukemia cells." (PMID 33924032, 2021). "HAP1 cells originate from experiments to induce pluripotency in the leukemia KBM7 cell line by transduction with KLF4, POU5F1 (Oct4), SOX2, and MYC." (PMID 33228647, 2020). "Embryonic stem cell markers Nanog, Oct-4, and SOX-2, the cancer stem cell marker CD133, and the leukemia stem cell marker (CD123) were examined." (PMID 28665981, 2017).
meningioma (10 papers, 2011 to 2024). A generally slow growing tumor attached to the dura mater. "In a previous study that used immunohistochemistry and real-time RT-PCR, we showed that the expression of the stemness marker Sox2 is associated with a worse prognosis independently from the WHO meningioma grade." (PMID 36836440, 2023). "In particular, we showed that Sox2-expressing grade 1 and 2 meningiomas are associated with an increased risk of progression to anaplastic tumors." (PMID 36836440, 2023). "The high expression of AGR2 has been previously associated with the expression of Nestin, CD133 and SOX2 in high-grade meningioma tissues." (PMID 36482387, 2022). "SOX2 expression was indeed strictly associated with meningioma grade." (PMID 36232992, 2022). "Importantly, SOX2 expression at first surgery was strongly related to meningioma clinical behavior, histological grade and risk of recurrence." (PMID 36232992, 2022). "VEGF, EGFR, EGFRvIII, PD-L1; and Sox2 expression; MGMT methylation status; and TERT promoter mutation were assessed in paired meningioma samples collected from the same patient before and after progression using immunohistochemistry and PCR." (PMID 36836440, 2023). "Herein, we evaluated the expression of SOX2 in a series of recurrent and progressive meningiomas in order to assess its prognostic role." (PMID 36232992, 2022). "Considering all samples, among grade 1 meningioma, 39.3% showed immunostaining for SOX2; among grade 2 meningioma, 72.9% were positive; among grade 3 meningioma, 94.3% were positive on IHC for SOX2 (p < 0.0001, Chi square test)." (PMID 36232992, 2022). "Confocal immunofluorescence using meningioma markers confirmed that the SOX2 signal resides in the nucleus." (PMID 36232992, 2022). "The purpose of the present work was to dissect the role of SOX2 in predicting the aggressiveness of meningioma." (PMID 36232992, 2022). "In the whole series, the fraction of SOX2-positive tumors on IHC was significantly correlated with the meningioma grade." (PMID 36232992, 2022). "Among them, high expression of SOX2 was associated with poor OS and PFS of meningioma patients." (PMID 38758750, 2024). "However, apart from Sox2, the paths of molecular evolution of anaplastic meningiomas largely remain to be investigated." (PMID 36836440, 2023). "Literature background on Sox2 and EGFRvIII role in meningioma is scarce." (PMID 36836440, 2023). "Alternatively, the close relationship between Sox2 and EGFRvIII may reflect the embryonic origin of the arachnoid membrane, whereby meningioma expresses both epithelial and mesodermal antigens." (PMID 36836440, 2023). "Among grade 2 meningioma, Group 2P, i.e., grade 2 meningioma undergoing anaplastic transformation, had a significantly higher percentage of SOX2-positive cases than Groups 2B and 2R (100 vs 47.4% and 100 vs 64.3%; p = 0.0016 and p = 0.0391, respectively; Fisher exact test)." (PMID 36232992, 2022). "The expression of SOX2 could distinguish those grade 1–2 meningiomas that have a favorable clinical course from those that behave aggressively, irrespective of their WHO grade." (PMID 36232992, 2022). "One hundred and eleven meningioma samples were available for SOX2 immunohistochemistry (IHC)." (PMID 36232992, 2022). "Since direct SOX2 inhibition is unfeasible due to inacceptable toxicity, the main pathways regulated by SOX2 in meningioma could be dissected and their inhibition explored." (PMID 36232992, 2022). "A recent immunohistochemical survey in GI meningiomas identified a number of SC markers, including OCT4, NANOG, SOX2, KLF4, and c-MYC, on microvessels that led to the suggestion that these vessels may be associated with meningioma initiation." (PMID 31083655, 2019). "These techniques made it possible to support the research theory that an overexpression of NANOG and other markers of pluripotency and stemness in meningiomas, such as SOX2 and OCT4, could be exploited to target potentially pluripotent "stem cell-like" cells." (PMID 29495368, 2018).
meningioma (continued). "SOX2 assessment is a promising, powerful molecular tool to accurately stratify the risk of recurrence and progression of disease since the very first diagnosis of meningioma, irrespective of WHO grade." (PMID 36232992, 2022). "Further, we assessed the clinical value of SOX2 expression in predicting the PFS and OS of meningiomas." (PMID 36232992, 2022). "Previous work in meningiomas revealed different co-expression patterns of PROM1 and SOX2 in tissues compared to corresponding cell lines." (PMID 31083655, 2019). "Whereas the average number of cells positive for both SOX2 and PROM1 significantly increased in GII + GIII meningioma cell lines, they significantly decreased in GII + GIII meningioma tissues compared to GI entities." (PMID 31083655, 2019). "An immunohistochemical study detected higher expression of nestin (NES), SOX2, and prominin 1 (PROM1), also known as CD133, in more progressive meningiomas." (PMID 31083655, 2019). "In meningioma cultures, cells with pleomorphic characteristics show markedly increased numbers of CSCs scoring positive for PROM1 and SOX2, or AGR2 and BMI1." (PMID 31083655, 2019). "Among grade 1 meningiomas, we found that the percentage of SOX2-positive tumors was significantly higher in Group 1P than in Group 1B, i.e., in progressive vs non-progressive grade 1 meningiomas (87.5 vs 20%, p = 0.0042, Fisher exact test)." (PMID 36232992, 2022). "Namely, SOX2 mRNA levels were remarkably lower in the IHC negative meningioma as compared with SOX2 IHC positive ones (relative medians 0.0350 [0.0085; 0.0710] vs 0.2400 [0.1018; 0.4665], p < 0.001, Mann–Whitney U test)." (PMID 36232992, 2022). "To summarize, SOX2 was shown to be a negative prognostic factor for recurrence and survival in meningioma patients." (PMID 36232992, 2022). "In particular, the average number of cells positive for both SOX2 and CD133 was lower in grade II/III meningiomas, while cells positive for SOX2 and negative CD133 increased in frequency." (PMID 29849507, 2018). "Meningioma tissues and primary cell lines were investigated using whole transcriptome microarray analysis, immunofluorescence staining of CSCs markers (including CD133, Sox2, Nestin, and Frizzled 9), and drug treatment with cisplatin or etoposide." (PMID 28736504, 2017). "The validation of the negative prognostic value of SOX2 in meningiomas might also prompt the development of targeted therapies that are able to inhibit the SOX2 pathway." (PMID 36232992, 2022). "The correlation of FZD9 with SOX2 is perhaps not surprising, giving that they are both part of the WNT signaling pathway, a pathway that is activated in some meningiomas." (PMID 29849507, 2018). "Notwithstanding the strong negative prognostic value of SOX2 expression, which has been widely addressed in this study, a small but non-negligible proportion of WHO grade 1, SOX2-positive meningiomas (20%) will eventually behave in a benign way and will not undergo recurrence or progression." (PMID 36232992, 2022).